IL10 (interleukin 10)
Diseases named in the same sentence as IL10 in open-access papers (continued):
Sharing a sentence is not in itself a finding about the gene and the disease.
diabetes (continued). "The results showed that blockade of IL-10/TGF-β bioactivities in vivo dramatically abrogated the suppressive effects of p524-expanded CD4+CD25+ T cells on adoptively transfer of diabetes." (PMID 19759824, 2009). "Therefore, it seems that the role of IL‐10 in immune regulation and diabetes progression is tissue‐specific." (PMID 40903907, 2025). "However, local overexpression of IL‐10 in the pancreatic islets of NOD mice exacerbates diabetes and promotes insulitis." (PMID 40903907, 2025). "In previous studies of CHF and diabetes patients, depressive symptoms were associated with higher levels of the proinflammatory cytokines TNF‐α, IL‐6, and CRP, and lower levels of the anti‐inflammatory cytokines IL‐10 and ADPN." (PMID 40700022, 2025). "Meanwhile, NC@Gel increased the level of IL-10 (10.79 % higher than that of the diabetes group)." (PMID 41169791, 2025). "Administration of genetically modified strains of Lactobacillus lactis that secrete pro-insulin autoantigen and the immunomodulatory cytokine IL-10 could revert diabetes in NOD mice and increase the frequencies of local T regulatory cells." (PMID 40422866, 2025). "In this study, we have identified a group of APMB-specific analytes (IL-10, CXCL1, IL-12p40, IL-13, CCL22, CCL4, IL-17A, and TGFα) that correlates with several clinical phenotypes associated with more severe SAB (diabetes, dialysis dependence, metastatic infection, and cardiac vegetation)." (PMID 39966757, 2025). "Interestingly, in those participants with diabetes where a response was detected, it was dominated by the secretion of IL‐10 that was present in most cytokine‐producing cells." (PMID 41367201, 2025). "Among anti-inflammatory factors, IL-10 plays a role in suppressing the immune response by inhibiting the release of inflammatory mediators from Th1 cells, potentially providing a protective effect in diabetes." (PMID 41293068, 2025). "Viewing an interaction conversely, we found several Th2 cytokines known to be highly expressed during helminth infection such as IL-4, IL-5, and IL-10 to also be influenced by concomitant diabetes (i.e., they had high DDI interaction term contributions of 42.79%, 36.51%, and 55.52% respectively)." (PMID 41174472, 2025). "The therapeutic value of IL-10 in the treatment of diabetes-related complications remains unclear and requires further investigation." (PMID 39125659, 2024). "We hypothesized that the injection of IL-10-treated adipose stromal cells could reverse diabetes-induced gluconeogenesis and insulin resistance by inducing Treg cells within the adipose tissue." (PMID 39125659, 2024). "IL10-conditioned DCs stopped the onset of diabetes in NOD mice." (PMID 38543910, 2024). "Our results suggest that IL-10-treated adipose stromal vascular cells could be a promising therapeutic strategy for treating diabetes mellitus." (PMID 39125659, 2024). "Collectively, we identified that the injection of IL-10-treated SVFs is capable of mitigating diabetes-induced adipose inflammation, liver gluconeogenesis, and insulin resistance, which may be mediated through an increase in Tregs in the adipose tissue." (PMID 39125659, 2024). "Thus, our results indicated that the microbiota of Tlr9fl/flCd19-Cre+ NOD mice are directly involved in diabetes protection by modulating the host immune tolerance through promoting the secretion of immune-regulatory cytokine IL-10." (PMID 38903498, 2024). "The present findings showed that voluntary exercise could have therapeutic effects on diabetes mellitus type 2, and it improved its pulmonary complication by elevation of the levels of Nrf2, IL-10, and IL-11 as well as decreasing TNF-α and NF-kB levels." (PMID 38164478, 2024). "Therefore, the increased cardiac concentrations of NFkB and IL-10 in the diabetic control group infer diabetes-instigated cardiac inflammation." (PMID 39239455, 2024).
diabetes (continued). "Subgroup A1 was characterized by significantly higher levels of IL-35 and IL-10 than the other subgroups of patients with diabetes, and statistically higher IL-4 when compared to subgroup B. Our study shows that the effect of metabolic memory fades away with the increasing duration of diabetes." (PMID 38542165, 2024). "In this study, the level of IL-10 was increased following purslane treatment in diabetes." (PMID 39596339, 2024). "The hypothesis that both OA and diabetes are based on imbalanced molecular pathways is further strengthened "with the putative crucial role of anti-inflammatory cytokines" such as Il-10." (PMID 37255905, 2023). "Interestingly, levels of IL-10 and IL-12p70 in brain lysates are significantly elevated in rats previously exposed to diabetes ketoacidosis when compared with diabetic rats alone." (PMID 36869375, 2023). "However, associations of IL-1β, IL-10, IL-12 p70, MCP-3, and TNF-α with TIR remained significant after adjustment to BMI, as well as other possible confounders (age, sex, diabetes duration, and eGFR)." (PMID 37893217, 2023). "This observed trend was also noticed in other animal models of high-fat diet or streptozotocin-induced diabetes, where probiotic Lactobacillus plantarum increased the expression of IL-10 while decreasing the expression of TNF-α and IL-6, providing immunomodulatory characteristics of probiotics." (PMID 37894792, 2023). "In addition, diabetes-induced increases in retinal inflammatory proteins iNOS, IL-1α, and IL-10, and ICAM-1 were also inhibited in STING-KO and STINGGT diabetic mice." (PMID 37345657, 2023). "On the other hand, a decreased secretion of anti-inflammatory cytokines such as transforming growth factor-beta (TGF-β), interleukin-4 (IL-4), and interleukin-10 (IL-10) may also lead to the aggravation of periodontal inflammation in diabetes patients." (PMID 37664859, 2023). "The anti-inflammatory IL-10 was downregulated by diabetes compared to MWF-C." (PMID 38069331, 2023). "In addition, PAP1 prevented the diabetes-induced repolarization defects through reducing the secretion of the inflammatory cytokines IL-10, IL-12p70, GM-CSF, IFNγ, and TNFα." (PMID 34623540, 2023). "It is hypothesized that there is decreased availability of the anti-inflammatory IL-10 in both OA and diabetes." (PMID 37255905, 2023). "IL-10, on the other hand, is an anti-inflammatory cytokine that attenuates the inflammatory processes, and it has been suggested to be protective against the development of diabetes and metabolic syndrome." (PMID 36290594, 2022). "In addition, studies have reported that IL-1β is inversely correlated with IL-10 in the healthy population; however, when diabetes mellitus occurs, the balance between anti-inflammatory IL-10 and proinflammatory IL-1β is broken." (PMID 36582230, 2022). "Moreover, wound administration of mouse Mφs activated IL-4 or IL-10 in vitro into the M2-like phenotype damaged skin wound healing in a diabetic mouse model." (PMID 36582221, 2022). "Since IL-10 is a known M2c trigger, we aimed to see if IL-10 depletion in microglia could prevent or reverse the M2c polarization of diabetes microglia and generate a positive effect on cerebral atherosclerosis." (PMID 35935990, 2022). "Experiments show that GMP can reduce the levels of IL-6, TNF- α, and CRP, increase the level of IL-10, and then alleviate the inflammatory reaction induced by diabetes and repair the phenomenon of hepatocyte lysis and inflammatory cell infiltration in mice, so as to improve the liver injury." (PMID 35399678, 2022). "Besides, the M1 polarization markers, including IL-1β, IL-6 and TNF-α increased in the isolated retinal microglia from diabetes rats, with the decreasing M2 polarization markers such as IL-4, IL-10 and TGF-β." (PMID 35300330, 2022). "However, the therapeutic values of IL-10 for the treatment of diabetes-related complications need to be clarified and require further investigation." (PMID 35883204, 2022).
diabetes (continued). "Here, we observed a marked alteration of the major pro- and anti-inflammatory cytokines involved in diabetes pathogenesis, including IL-10, IL-6, and TNF-α in the diabetic rats, which significantly attenuated after treatment by heat-killed Actinomycetales species." (PMID 33880360, 2021). "Interestingly, 60% of NOD mice were prevented from developing diabetes (Log-rank Mantel-Cox, p = 0.03) when treated with either PI+TGFβ or PI+IL10 plus anti-CD3 mAb compared to vehicle." (PMID 34108968, 2021). "These speculations warrant further investigation to determine the contribution of IL-10 resistance to severe COVID-19 outcomes in individuals with diabetes." (PMID 34234779, 2021). "Recent work from our group has demonstrated that NOD mice that developed diabetes showed a reduced splenic IL-10+ B cell population, measured by intracytoplasmic staining, compared to mice that were long-term normoglycemic or ‘naturally-protected’ from diabetes (>35 weeks old)." (PMID 34616408, 2021). "Based on these observations, it is tempting to speculate that a similar resistance to IL-10’s anti-inflammatory action may underpin hyperinflammation in COVID-19, particularly in individuals with diabetes." (PMID 34234779, 2021). "Moreover, when we transferred total splenocytes from non-diabetic BDC2.5+Il-10-/- or BDC2.5+Il-10+/+ NOD mice into NOD.scid mice, splenocytes from BDC2.5+Il-10-/- mice induced rapid diabetes in the NOD.scid recipients as early as 3-days after transfer." (PMID 34394099, 2021). "Il-10, secreted among others by macrophages, is recognized as a cytokine presenting antiangiogenic, anti-inflammatory, and antiatherogenic, as well as diabetes-protective, action." (PMID 34944529, 2021). "Interestingly, targeting of B cells via the blockade of the B cell activating factor (BAFF) induced an increase of IL-10+ B cells and diabetes protection." (PMID 34616408, 2021). "Interestingly, both female and male BDC2.5+Il-10-/- NOD mice developed accelerated diabetes at a very young age." (PMID 34394099, 2021). "Although 200mg/kg of SE in the G1 mice significantlyincreased the percentage of Treg cells, it did not control FBS and other symptoms ofdiabetes, while 400 mg/kg of SE in theG2 mice significantly increased both the Treg numberand IL-10 level, controlled diabetes symptoms and reduced FBS." (PMID 34455723, 2021). "Moreover, genome-wide association studies (GWAS) have identified that ABO blood groups gene as a locus for diabetes mellitus and many inflammatory biomarkers, such as IL-10, soluble E-selectin, P-selectin and intercellular adhesive molecule 1 (ICAM-1)." (PMID 33143655, 2020). "The relation between IL-10 and diabetes needs further research." (PMID 33382747, 2020). "However, higher values of IL-10 were noted to patients with neuropathic pain as a result of diabetes." (PMID 32038662, 2020). "Polymorphisms of genes encoding pro- and anti-inflammatory cytokines (TNFα-308 G/A, IFNγ +874 A/T, IL-10–1082G) may be responsible for nerve damage in neuropathy, which is a common complication of diabetes." (PMID 32751810, 2020). "There was a significantly opposite trend in TNF-α, IL-1β, and IL-10 between the n-3 Adq-GDM group and n-3 Def-GDM group, which could lead to differential diabetes risk." (PMID 31340612, 2019). "IL-10 production is related to genetic variations in its promoter region, and this region controls transcription and contains SNPs that are related to diabetes and its complication." (PMID 30873205, 2019). "Therefore, we also proposed that upregulation of IL-10 as a protective mechanism in the HFD-induced diabetic heart attenuates immune response and facilitates cell survival." (PMID 31886288, 2019). "Intestinal IL10-producing Tr1 cells decrease diabetes incidence in NOD mice." (PMID 30863412, 2019).
diabetes (continued). "Increased glycation is known to inhibit IL-10 and TNFα production by immune cells, which suggests that the lower cytokine production may be a consequence of diabetes-mediated intrinsic defect in these cells." (PMID 29996768, 2018). "Finally, in the study addressing the effect of FBS on mechanisms of tolDC-action in NOD mice, only GM-CSF and IL-10 generated tolDCs pulsed with 2 insulin B chain peptides prevented diabetes in NOD mice." (PMID 29503651, 2018). "Expression levels of the inhibitory cytokines Il-10 and Tgf-β were generally unaffected during infection and/or diabetes, likely reflecting the impairment of immune response in diabetes and participation of the cytokines in pathogenesis during liver fluke infection." (PMID 29953446, 2018). "In addition, our data confirmed that the pain behavior coincided with the expression changes of inflammatory cytokines (TNF-α, IL-1β, IL-6, and IL-10) in rats with diabetes induced by STZ." (PMID 29713362, 2018). "As it has been shown recently that Type 1 interferon inhibits IL-10 signaling and development of diabetes in NOD mice which is promoted by IL-33, the mechanism may be similar." (PMID 30498495, 2018). "hASC and hASC-CM treatments were able to normalize cytokine levels, as demonstrated by the IFN-γ and IL-2 decrease (p < 0.001 vs STZ) and IL-10 and IL-4 increase when treatments were performed 6 weeks after diabetes induction and cytokines measured 8 weeks later." (PMID 28851944, 2017). "On the other hand, enhanced IFN-γ production increased susceptibility to MLD-STZ-induced type 1 DM; while downregulation of Th2 cells (and so decrease in the production of IL-4 and IL-10) downregulated the disease; and inhibition of IL-1 activity downregulated diabetes induction." (PMID 28824543, 2017). "TNF-α and IL-10 blood levels increased because of diabetes and periodontal disease (p < 0.05)." (PMID 28906456, 2017). "Functionally, IL-10 secreted by ICOS+ Treg contributed to their function in preventing diabetes." (PMID 29033948, 2017). "Interestingly both hASC and hASC-CM were fully effective in reverting allodynia and restoring IL-1β, /IL-10 spinal cord balance also when injected 6 weeks after diabetes induction." (PMID 28851944, 2017). "Furthermore, it has been suggested that low levelsof IL-10 correlate with the pathogenesis of diabetes." (PMID 27074164, 2016). "Moreover, concomitant with suppression in Th17, immunoregulatory induced generation of Treg cells that are important in the control of diabetes with a concomitant increased level of IL-10 production and decreased in IL-6 and IFN-γ." (PMID 27165305, 2016). "In vivo inhibition of NFAT with A-285222 decreased the expression of OPN and ICAM-1 mRNA in retinal vessels, prevented a diabetes driven downregulation of anti-inflammatory IL-10 in retina, and abrogated the increased vascular permeability observed in diabetic mice." (PMID 25918731, 2015). "There are no studies in the literature investigating the expression of proinflammatory(IFN-γ, TNF-α, IL-17A) and anti-inflammatory (IL-4, IL-10) cytokines in serum ofpatients with type 2 diabetes mellitus submitted to duodenojejunal bypass surgery withileal interposition without gastric resection." (PMID 26734798, 2015). "In addition, IL-10 over-expression can inhibit IL-1β-induced Fas expression and apoptosis of insulin secreting cells, reduce the incidence of diabetes of prediabetic NOD mice, and delay or even prevent T1D development." (PMID 24663217, 2014). "Notably, organ-specific IL-10 production has been identified to evoke autoimmunity in a mouse model of diabetes." (PMID 25181038, 2014). "IL-10 has been shown to protect against diabetes in NOD mice but only when administered from an early age, and thus the reduction in IL-10 levels we observed might not have an influence on autoimmunity." (PMID 25390735, 2014).
diabetes (continued). "There was one notable interaction between INS genotype and T1D status, however, in which antigen-specific T cells from control subjects with the diabetes-protective proinsulin VNTR III preferentially expressed IL-10, IL-2, and FASLG, genes known to participate in potent regulatory pathways." (PMID 24844227, 2014). "Moreover anti-CD3 plus LL-PINS reversed diabetes in 49% of treated mice highlighting the importance of mucosal co-delivery of IL-10 and Ag." (PMID 25185797, 2014). "The authors reported 74.4% of subjects negative for IL-10 -824 T allele were diabetic patients characterized by vascular damages, suggesting that IL10 -597A/-824 T/-1087A negative subjects are more prone to the major type 2 diabetic vascular damages." (PMID 23941335, 2013). "Surprisingly, local production of IL-10 in islets accelerated the onset and increased the prevalence of diabetes, suggesting that IL-10 may have diverse functions in addition to its immunoinhibitory effects." (PMID 23671851, 2013). "On the other hand, IL-10 appears to also play an important role in diabetes prevention." (PMID 21716731, 2011). "Furthermore, systemic delivery of IL-10 by intramuscular injection of expression plasmid DNA can prevent diabetes in NOD mice." (PMID 21716731, 2011). "On the one hand, there is evidence that IL-10 is involved at some level in diabetes pathogenesis." (PMID 21716731, 2011). "We propose that cytokine profiles, particularly IL-12 and IL-10, could be useful predictors of the ability of stimuli to induce DCs that may be used as a treatment for the prevention of diabetes." (PMID 21716731, 2011). "We next tested whether injections of LC-treated NOD DCs in NOD mice could actually prevent diabetes development in an IL-10 dependent manner." (PMID 21716731, 2011). "We finally tested whether the production of IL-10 by LC-treated DCs was responsible for the decrease in diabetes incidence." (PMID 21716731, 2011). "Intraperitoneal injection of a long-lived noncytolytic murine IL-10/Fc fusion protein into young NOD mice prevents insulitis and diabetes by blocking the production of proinflammatory cytokines and IFNγ, and IL-10-transduced islet-specific CD4+ T-cells prevent diabetes transfer in NOD mice." (PMID 21716731, 2011). "In this setting, we also examined whether IL-10/TGF-β cytokines played an essential role in p524-expanded CD4+CD25+ T cell-mediated delayed development of diabetes." (PMID 19759824, 2009). "Furthermore, neutralizing antibodies to IL-10/TGF-β were administrated to evaluate the role of IL-10/TGF-β in p524-expanded CD4+CD25+ T cell-mediated prevention from diabetes transfer." (PMID 19759824, 2009). "However, IL-10 levels are often reduced in diabetes, leading to uncontrolled inflammation." (PMID 41011276, 2025). "Additionally, the increases in IL-4 and IL-10 levels point to a shift towards an anti-inflammatory state, promoting a favourable immunological environment that could benefit diabetes management by mitigating chronic inflammation." (PMID 40299229, 2025). "Furthermore, IL-10 plays a protective role in bone metabolism; mice lacking IL-10 exhibited enhanced bone loss and reduced osteoblast function under hyperglycemic stress, highlighting IL-10’s relevance in diabetes-associated bone complications." (PMID 40804870, 2025). "Furthermore, a shift towards an anti-inflammatory state is indicated by the increases in IL-4 and IL-10 levels, which could help manage diabetes by reducing chronic inflammation and creating a favourable immunological environment." (PMID 40299229, 2025). "The decreased cardiac concentration of NFkB and IL-10 in the diabetic rats following supplementation with Brazil nut, metformin, or combination of both suggests the protective action of Brazil nut, metformin, or combination of both against diabetes-induced cardiac inflammation." (PMID 39239455, 2024).